COG5 (component of oligomeric golgi complex 5)
Description:
Required for normal Golgi function.
Synonyms: GOLTC1; GTC90; CDG2I
Tractability: Antibody: UniProt places it where antibodies can reach, with high confidence. PROTAC: ubiquitination databases record sites on it; its protein half-life has been measured.
Target class: Other cytosolic protein
Gene: Protein-coding gene on chromosome 7 (107,201,372 to 107,564,261, reverse strand). Ensembl gene ENSG00000164597.
Subcellular location: Cytoplasm, cytosol; Golgi apparatus membrane
Subcellular location (Human Protein Atlas): Golgi apparatus; Nucleoplasm
Pathways (Reactome):
Vesicle-mediated transport: COPI-mediated anterograde transport; Intra-Golgi traffic; Retrograde transport at the Trans-Golgi-Network
Gene Ontology:
Molecular function: protein binding
Biological process: Golgi organization; inter-Golgi cisterna vesicle-mediated transport; retrograde transport, vesicle recycling within Golgi; intra-Golgi vesicle-mediated transport
Cellular component: Golgi apparatus; Golgi transport complex; membrane; Golgi membrane; trans-Golgi network membrane; cytosol
Genetic constraint (gnomAD): Loss-of-function variants: 59 observed, 71.41 expected, observed/expected ratio (o/e) 0.83, 90% interval 0.67 to 1.03. The upper end of that interval is the gene's LOEUF score, 1.03, which puts it in group 4 of 6, group 1 being the genes least tolerant of losing a copy. Missense variants: 827 observed, 785.78 expected, observed/expected ratio (o/e) 1.05, 90% interval 0.99 to 1.12. Synonymous variants: 282 observed, 275.99 expected, observed/expected ratio (o/e) 1.02, 90% interval 0.93 to 1.13.
Gene-disease validity (ClinGen):
ClinGen rates the evidence that COG5 causes each of these diseases.
COG5-congenital disorder of glycosylation (autosomal recessive): Definitive. COG5-CDG is an extremely rare form of CDG syndrome characterized clinically in the single reported case to date by moderate mental retardation with slow and inarticulate speech, truncal ataxia, and mild hypotonia.
Homologues: Orthologues: chimpanzee COG5 (99% identical), macaque COG5 (99% identical), dog COG5 (94% identical), guinea pig COG5 (93% identical), rabbit COG5 (91% identical), mouse Cog5 (89% identical), pig COG5 (89% identical), rat Cog5 (87% identical), tropical clawed frog cog5 (82% identical), Drosophila melanogaster fws (26% identical), Caenorhabditis elegans cogc-5 (21% identical), zebrafish cog5 (17% identical).
Diseases named in the same sentence as COG5 in open-access papers:
COG5 is named in the same sentence as 48 diseases in open-access papers, as found by Europe PMC text mining. Sharing a sentence is not in itself a finding about the gene and the disease. The quoted sentences say what the papers report.
congenital disorder of glycosylation (3 papers, 2020 to 2026). Congenital disorder of glycosylation (CDG) is a fast growing group of inborn errors of metabolism characterized by defective activity of enzymes that participate in glycosylation (modification of proteins and other macromolecules by adding and processing of oligosaccharide side chains). "This study reports a Chinese patient with a Congenital Disorder of Glycosylation (CDG) caused by compound-heterozygous mutations in the Conserved Oligomeric Golgi 5 (COG5) gene and thereby offers concrete evidence for early diagnosis." (PMID 32174980, 2020). "Patient 7 also carried heterozygous variants in ALG1 and COG5 genes causative of the autosomal recessive disorders: congenital disorder of glycosylation (CDG), type Ik; and CDG, type III, respectively." (PMID 39202394, 2024).
microcephaly (2 papers, 2019 to 2020). A congenital or acquired developmental disorder in which the circumference of the head is smaller than normal for the person's age and sex. "Here we identified COG5 compound-heterozygous variants in patients affected with a complex LCA phenotype associated with microcephaly and skeletal dysplasia." (PMID 33277529, 2020). "Hence, COG5 becomes a candidate gene for complex retinal degeneration, especially when short stature and microcephaly are present." (PMID 33277529, 2020). "This study identifies a novel role for COG5 in maintaining ER protein homeostasis and that disruption of that role results in activation of PERK and early-onset retinal degeneration, microcephaly and skeletal dysplasia." (PMID 33277529, 2020).
osteoarthritis (2 papers, 2013 to 2024). A noninflammatory degenerative joint disease occurring chiefly in older persons, characterized by degeneration of the articular cartilage, hypertrophy of bone at the margins and changes in the synovial membrane. "Another relevant osteoarthritis-related gene is the COG5 gene which is an integral part of the conserved oligomeric Golgi (COG) complex, which plays an essential role in maintaining Golgi apparatus structure and function." (PMID 38665758, 2024). "Notably, the COG5 gene from the C7q22 region associated with osteoarthritis susceptibility has been extensively researched for its involvement in glycosylation defects, chondrogenesis and osteogenesis, Wnt signaling, as well as inhibition of COG5 gene expression." (PMID 38665758, 2024).
autism (1 paper, 2014). Persistent deficits in social interaction and communication and interaction as well as a markedly restricted repertoire of activity and interest as well as repetitive patterns of behavior. "This small deletion included the COG5 gene which is located in the autism susceptibility 1 (AUTS1) locus known to cause atypical development and autism supporting an underlying cause of his developmental/behavioral problems." (PMID 25400949, 2014).
chondrosarcoma (1 paper, 2022). A malignant cartilaginous matrix-producing mesenchymal neoplasm arising from the bone and soft tissue. "COG5 is involved in metastatic inflammation and cartilage formation and can represent a prospective treatment target for chondrosarcoma." (PMID 35884444, 2022).
cone-rod dystrophy (1 paper, 2020). Inherited retinal dystrophies that belong to the group of pigmentary retinopathies. "We noted that within the same sections, cone photoreceptor inner segments often had a higher COG5 staining intensity compared to neighboring rod photoreceptor inner segments, which could support the cone-rod dystrophy phenotype observed." (PMID 33277529, 2020).
COVID-19 (1 paper, 2022). A disease caused by infection with severe acute respiratory syndrome coronavirus 2. "Twelve proteins showed lower levels in critical patients (fold-changes 1.20–3.58), of which OAS3 and COG5 found their expression increased after COVID-19 specific therapy." (PMID 35022497, 2022).
Friedreich ataxia (1 paper, 2020). An inherited condition that affects the nervous system and causes movement problems. "To date, variants in COG5 have been associated with a distinct congenital disorder of glycosylation (type IIi) and with a variant of Friedreich’s ataxia." (PMID 33277529, 2020).
immune deficiency (1 paper, 2020). "Furthermore, no immune deficiency has been reported in any COG5-CDG patients." (PMID 32174980, 2020).
Leigh syndrome (1 paper, 2026). A progressive neurological disease defined by specific neuropathological features associating brainstem and basal ganglia lesions. "Additionally, we identified a patient with biallelic COG5 variants presenting with a distinct subtype of mitochondrial disease (Leigh syndrome), a phenotype not previously associated with COG5-related disorders." (PMID 41824529, 2026).
non-small cell lung carcinoma (1 paper, 2017). A group of at least three distinct histological types of lung cancer, including non-small cell squamous cell carcinoma, adenocarcinoma, and large cell carcinoma. "Although Cog5 was a newly identified reference gene in fish, previous studies of human non-small cell lung cancer and thyroid cancer used this gene as an internal control." (PMID 28182746, 2017).
renal carcinoma (1 paper, 2025). A carcinoma arising from the epithelium of the renal parenchyma or the renal pelvis.
retinal degeneration (1 paper, 2020). Degeneration of the retina. "Our study described for the first time novel relationships between COG5 subunit variants, UPR activation, DNA damage, and subsequent retinal degeneration in humans without neurocognitive impairment." (PMID 33277529, 2020).
cancer (2 papers, 2012 to 2022). A tumor composed of atypical neoplastic, often pleomorphic cells that invade other tissues. "For instance, the Greedy Decision Forest selected a module comprising of three genes for the cancer type experiment, namely COG1, COG3, and COG5." (PMID 36207536, 2022).
infection (1 paper, 2025). The state of being infected such as from the introduction of a foreign agent such as serum, vaccine, antigenic substance or organism. "For instance, among the genes upregulated in infected wild‐caught birds reported here, RAB20 was also upregulated in 'amakihi surviving experimental infection, and three upregulated genes (COG5, BOD1, and PCDH10 which activates PCDHGA6) were downregulated in 'amakihi that perished." (PMID 40909016, 2025).
tumour (1 paper, 2021). "mRNA expression levels of COG subtypes depended on the tumour grade, especially COG4, COG5, COG6, COG7, and COG8." (PMID 34539936, 2021). "Similarly, high mRNA expression of 5 of all COG isoforms (COG2, COG3, COG5, COG6, COG7, and COG8) was also correlated with favourable OS of KIRC patients with tumour grade 2, grade 3, and grade 4, while patients with low mRNA expression of COG4 showed higher survival rate." (PMID 34539936, 2021).
COG5 also shares sentences with these, for which no sentence is quoted: optic atrophy (2 papers); 3-methylglutaconic aciduria (1); Birk-Landau-Perez syndrome (1); brachydactyly (1); breast carcinoma (1); Cerebellar atrophy (1); colorectal cancer (1); cryptorchidism (1); developmental delay (1); dihydrolipoamide dehydrogenase deficiency (1); dysplasia (1); Failure to thrive (1); hand osteoarthritis (1); Hydrops (1); hypertrophic cardiomyopathy (1); keratosis pilaris (1); kidney stones (1); Lesch-Nyhan syndrome (1); metabolic disorder (1); mitochondrial disease (1); mucopolysaccharidosis type 2 (1); Neurodevelopmental delay (1); neurologic disease (1); neuronal ceroid lipofuscinosis (1); Obesity (1); primordial dwarfism (1); prostate carcinoma (1); pulmonary embolism (1); scoliosis (1); skeletal dysplasia (1).
A further 2 diseases each share a sentence with COG5 in 1 paper.